HYAL3 (hyaluronidase 3)
Description:
Facilitates sperm penetration into the layer of cumulus cells surrounding the egg by digesting hyaluronic acid. Involved in induction of the acrosome reaction in the sperm. Involved in follicular atresia, the breakdown of immature ovarian follicles that are not selected to ovulate. Induces ovarian granulosa cell apoptosis, possibly via apoptotic signaling pathway involving CASP8 and CASP3 activation, and poly(ADP-ribose) polymerase (PARP) cleavage. Has no hyaluronidase activity in embryonic fibroblasts in vitro. Has no hyaluronidase activity in granulosa cells in vitro.
Synonyms: Hyal-3; LuCa-3; LUCA3; LUCA14; Minna14
Tractability: Antibody: UniProt places it where antibodies can reach, with medium confidence; UniProt predicts a signal peptide or a membrane-spanning region; its Gene Ontology location is reachable by antibodies, with medium confidence.
Gene: Protein-coding gene on chromosome 3 (50,292,831 to 50,299,405, reverse strand). Ensembl gene ENSG00000186792.
Subcellular location: Secreted; Cell membrane; Cytoplasmic vesicle, secretory vesicle, acrosome; Endoplasmic reticulum; Early endosome
Pathways (Reactome):
Metabolism: CS/DS degradation; Hyaluronan degradation
Gene Ontology:
Molecular function: hyaluronoglucuronidase activity; hyalurononglucosaminidase activity; protein binding; virus receptor activity
Biological process: cartilage development; cellular response to interleukin-1; cellular response to tumor necrosis factor; cellular response to UV-B; hyaluronan catabolic process; inflammatory response; response to antibiotic; response to virus; negative regulation of ovarian follicle development; ovarian follicle atresia; penetration of zona pellucida; positive regulation of acrosomal vesicle exocytosis; carbohydrate metabolic process
Cellular component: cytoplasmic vesicle; lysosome; acrosomal membrane; acrosomal vesicle; early endosome; endoplasmic reticulum; extracellular region; plasma membrane; sperm midpiece
Genetic constraint (gnomAD): Loss-of-function variants: 33 observed, 40.33 expected, observed/expected ratio (o/e) 0.82, 90% interval 0.62 to 1.09. The upper end of that interval is the gene's LOEUF score, 1.09, which puts it in group 4 of 6, group 1 being the genes least tolerant of losing a copy. Missense variants: 442 observed, 559.71 expected, observed/expected ratio (o/e) 0.79, 90% interval 0.73 to 0.85. Synonymous variants: 215 observed, 224.43 expected, observed/expected ratio (o/e) 0.96, 90% interval 0.86 to 1.07.
Homologues: Orthologues: chimpanzee HYAL3 (99% identical), macaque HYAL3 (97% identical), guinea pig HYAL3 (84% identical), rabbit HYAL3 (83% identical), pig HYAL3 (78% identical), mouse Hyal3 (78% identical), rat Hyal3 (73% identical), zebrafish hyal3 (42% identical), Caenorhabditis elegans chhy-1 (27% identical). Paralogues in human: HYAL2 (42% identical), HYAL1 (41% identical), SPAM1 (37% identical), HYAL4 (36% identical).
Diseases named in the same sentence as HYAL3 in open-access papers:
HYAL3 is named in the same sentence as 20 diseases in open-access papers, as found by Europe PMC text mining. Sharing a sentence is not in itself a finding about the gene and the disease. The quoted sentences say what the papers report.
breast carcinoma (3 papers, 2016 to 2022). "In a study based on breast cancer cell lines, HYAL3 mRNA expression was demonstrated to be associated with low invasive potential." (PMID 36467500, 2022). "Here, we report a distinct and selective response to estrogen among the 3p21.3 locus genes in breast cancer cells, where the HYAL1 gene was repressed as compared to HYAL2 and HYAL3, and to other genes tested within the cluster." (PMID 27764788, 2016). "This negative regulation of HYAL1 by ERα provides a mechanism supporting the specific inverse correlation we found between ESR1 and HYAL1, but not with HYAL2 or HYAL3 in the METABRIC cohort consisting of 1980 cases of breast cancer." (PMID 27764788, 2016).
lung carcinoma (2 papers, 2022 to 2024). "In another study, high expression of the HYAL3-v1 splice variant was found to be associated with a better prognosis in lung carcinomas." (PMID 36467500, 2022). "The human hyaluronidase genes on chromosome 3p21.3 were first identified in a 630 kbp interval that was frequently deleted in LUng Cancer as LUCA1 (HYAL1), LUCA2 (HYAL2) and LUCA3 (HYAL3)." (PMID 39056785, 2024).
pancreatic cancer (2 papers, 2021 to 2023). "Reports substantiate high expressions of endogenous HYAL2 and HYAL3 in different pancreatic cancer cell lines including the Panc-1, and a negligibly low level of HYAL1." (PMID 33572222, 2021).
attention deficit-hyperactivity disorder (1 paper, 2023). A disorder characterized by a marked pattern of inattention and/or hyperactivity-impulsivity that is inconsistent with developmental level and clearly interferes with functioning in at least two settings (e.g. at home and at school). "A genome-wide association study analysis showed that HYAL3 is one of the pathogenic genes of attention-deficit hyperactivity disorder." (PMID 37528852, 2023).
colorectal cancer (1 paper, 2022). A primary or metastatic malignant neoplasm that affects the colon or rectum. "Prior research has suggested that HYAL3 promotes tumor growth in colorectal cancer." (PMID 35945500, 2022).
glioma (1 paper, 2023). A benign or malignant brain and spinal cord tumor that arises from glial cells (astrocytes, oligodendrocytes, ependymal cells). "In TCGA and GEPIA databases, we found that among the 6 human hyaluronidases (HYAL1, HYAL2, HYAL3, HYAL4, HYALP1, SPAM1), only HYAL2 expression was highest in glioma." (PMID 37568202, 2023). "In the present study, our results confirmed that among the six hyaluronidases (HYAL1, HYAL2, HYAL3, HYAL4, HYALP1, SPAM1), only HYAL2 was overexpressed in glioma patients, and HYAL2 overexpression was negatively correlated with the survival time of glioma patients." (PMID 37568202, 2023).
male infertility (1 paper, 2024). The inability of the male to effect fertilization of an ovum after a specified period of unprotected intercourse. "HYAL3 variants were reported in a single study as the autosomal recessive cause of male infertility associated with oligospermia." (PMID 39056785, 2024). "Sequencing of the HYAL3 coding region was carried out for 11 subjects from Pakistan with male infertility, 7 due to oligospermia and 4 with secondary infertility." (PMID 39056785, 2024).
melanoma (1 paper, 2025). A malignant, usually aggressive tumor composed of atypical, neoplastic melanocytes. "Inversely, HYAL3 was not detectable in melanoma cells but was strongly expressed in melanocytes, where its expression was further elevated by PACAP." (PMID 41465475, 2025).
ovarian carcinoma (1 paper, 2022). A malignant neoplasm originating from the surface ovarian epithelium. "Lower HAS2 expression and high expression of HYAL2 and HYAL3 favours the survival of ovarian cancer patients." (PMID 35767191, 2022). "HAS1, HYAL1 and HYAL4 mRNA expression is significantly upregulated, whereas HAS2, HYAL2 and HYAL3 mRNA expression is significantly downregulated in ovarian cancer tissue compared to controls." (PMID 35767191, 2022). "Our TNMplot analysis of over 700 ovarian cancer specimens revealed that HAS1, HYAL1 and HYAL4 mRNA expression is significantly upregulated, whereas HAS2, HYAL2 and HYAL3 mRNA expression is significantly downregulated in ovarian cancer tissue compared to controls." (PMID 35767191, 2022). "Following an evaluation of hyaluronan-related gene expression in the ATCC ovarian cancer panel, we studied SKOV3 and SW 626 ovarian cancer cells subjected to HAS2 siRNA or control siRNA treatment in terms of HAS1-3, HYAL2 and HYAL3 mRNA expression." (PMID 35767191, 2022).
teratocarcinoma (1 paper, 2022). A germ cell tumor characterized by the presence of an embryonal carcinoma component and a teratoma component. "HAS1, HAS2 and HYAL3 expression levels showed to be comparable in all adenocarcinoma cell lines SKOV-3, Caov-3 and SW 626 cells, whereas the teratocarcinoma cell line PA-1 cells expressed higher levels of all the three genes." (PMID 35767191, 2022).
tumor (6 papers, 2020 to 2023). "Similar results were observed in tumor associated fibroblasts isolated from WT mice, with the exception that 1,25D3 up-regulated Hyal3 in fibroblasts." (PMID 32774770, 2020). "HYAL3 belongs to the group of genes located on chromosome 3p21.3 that exhibit an association with tumor suppression; furthermore, the expression of specific transcript variants may parallel the tumor status." (PMID 35945500, 2022). "Although an association between HYAL3 and tumor development has been reported, the mechanism through which HYAL3 regulates tumor phenotypes remains unknown." (PMID 35945500, 2022). "In contrast, the expression of HAS2 (fold change = 1.42), HYAL2 (fold change = 1.84) and HYAL3 (fold change = 1.94) was significantly increased in the tumour tissue." (PMID 35767191, 2022). "Finally, we harnessed the Tumor IMmune Estimation Resource and Gene Expression Profiling Interactive Analysis to obtain correlations between HYAL3 expression, infiltrating immunocytes, and the corresponding immune marker sets." (PMID 35945500, 2022). "Altogether, these results support our findings that HYAL3 may participate in encoding HYAL and regulating tumor microenvironment-infiltrating immunocytes." (PMID 35945500, 2022). "We further used the Tumor IMmune Estimation Resource (TIMER) and the Gene Expression Profiling Interactive Analysis (GEPIA) databases to analyze the associations between the HYAL3 expression level, the type of infiltrating immunocytes, and their corresponding gene marker sets." (PMID 35945500, 2022). "In addition, it could be researched more closely, if the possible connection between the expression of HAS2 and HYAL3 has a consequence for example for HA production or tumour cell behaviour." (PMID 35767191, 2022). "Since HA undergoes dynamic regulation by HYALs, we evaluated the expression of HYAL1, HYAL2, and HYAL3 by RT-qPCR in three normal pancreatic tissue samples and seven PDAC tumor specimens." (PMID 37296612, 2023). "Interestingly, in our system, significantly increased expression of synthases (HAS2, HAS3) and hyaluronidases (HYAL1, HYAL3, HYAL4) was detected in the tumor cells but not in the stromal portion of TW2.6 tumors." (PMID 34869001, 2021). "When comparing TT and NAT, we noticed a high variability of HAS2, HAS3 and HYAL2 among the patients for both tumor types while HAS1 and HYAL3 could not be detected." (PMID 32610620, 2020).
cancer (4 papers, 2010 to 2022). A tumor composed of atypical neoplastic, often pleomorphic cells that invade other tissues. "HYAL3 mRNA was expressed as wild-type and variant 1–3 form, the latter more highly in primary carcinomas and effusions compared to solid metastases (p = 0.006)." (PMID 23202930, 2012). "To explore the role of HYAL3 in the development of BLCA, we analyzed the mRNA-sequencing expression levels of HYAL3 in various types of cancer." (PMID 35945500, 2022). "HYAL2-var2 mRNA was more highly expressed in solid metastases compared to effusions and primary carcinomas, whereas the opposite was true for HYAL3-var1-3." (PMID 23202930, 2012). "The late stages of cancer (C2 and D) seemed to prefer mostly the synergistic action of Hyal-1, PH-20 and Hyal-3." (PMID 20849597, 2010). "The results indicated that HYAL3 might serve as an oncogene in the development of cancers including BLCA." (PMID 35945500, 2022). "HYAL3 expression varied greatly between many types of cancers." (PMID 35945500, 2022). "However, expression levels were higher in primary carcinomas and effusions compared to solid metastases, this difference being a trend for HYAL3-WT (p = 0.099) and significant for HYAL3-var1-3 (p = 0.006)." (PMID 23202930, 2012).
genetic disorders (1 paper, 2024). "Of these, only deficiencies in HYAL1, HYAL2, HYAL3 and CEMIP have been identified as the cause or putative cause of human genetic disorders." (PMID 39056785, 2024).
HYAL3 also shares sentences with these, for which no sentence is quoted: adenocarcinoma (1 paper); breast tumors (1); cardiomyopathy (1); dysplasia (1); myocardial infarction (1); oligospermia (1); pulmonary arterial hypertension (1).